BCL2 (BCL2 apoptosis regulator)
Diseases named in the same sentence as BCL2 in open-access papers (continued):
Sharing a sentence is not in itself a finding about the gene and the disease.
tumor (continued). "Further investigation revealed that the downregulation of VGLL4 upregulated the expression of apoptosis-related Bcl-2 and the cell-cycle regulators Cyclin D1, Cyclin E1, and CDK8, and the upregulation of these molecules was conducive to tumor proliferation." (PMID 31748508, 2019). "Eight miRNA-449-family target genes (CDC25A, SIRT1, GMNN, E2F1, E2F3, BCL2, CDK2, and CCNE2) were selected; all of them involved in tumor development, cell cycle, and apoptosis." (PMID 30926829, 2019). "In vivo studies showed nuclear localization in tumor cells, reduction of about 80% of the tumor growth in mice, and reduction of KRAS and BCL-2 protein levels in treated tumors." (PMID 30682828, 2019). "Consistent with the primary tumour, immunohistochemical analyses also revealed focal positivity for CD99 and diffuse positivity for Bcl-2 and WT1." (PMID 31676869, 2019). "It is an important feature of the tumor microenvironment that can increase tumor survival rate and its progression by the regulation of CHOP and BCL-2 (B-cell leukemia/lymphoma-2) protein family members." (PMID 30863482, 2019). "The survival of tumor cells, as well as normal cells, is promoted by anti-apoptotic BCL-2-family members, including BCL-2, BCL-XL, and MCL1, which bind and sequester BH3-only proteins, thus preventing them from activating BAX and BAK." (PMID 30008477, 2019). "PTGS2 is overexpressed in TNBC, and promotes metastasis by regulating crucial molecules (Bcl-2, MRP4, PGT, 15-PGDH, TGFβ, etc.)involved in multiple tumor-promoting signaling pathways." (PMID 31690011, 2019). "XPO1 and BCL2 inhibitors synergize in vitro to induce apoptosis in DHL tumor cells, and most importantly, block tumor progression and dissemination in vivo." (PMID 31752970, 2019). "As expected, the levels of Bcl-2 in carcinogen treated animals were elevated and treatment with POL-PLGA-NPs to tumor-bearing animals reduces the Bcl-2 protein level." (PMID 31491872, 2019). "One such approach is the “BH3 profiling” of tumor cells, in which BH3 peptides interacting with Bcl-2, Bcl-xl, or Mcl-1 are used to identify the dependence of tumor cells on the respective anti-apoptotic Bcl-2 proteins." (PMID 31312616, 2019). "CD34, Bcl-2, and CD99 have been recognized as a representative marker of SFT, but they can also be positive in other neoplasms." (PMID 31520184, 2019). "In contrast, miR-34a has been identified as a tumor suppressor miRNA by repressing several target genes, such as cyclin-dependent kinase 4 (CDK4), CDK6, BCL2, MET, Notch, c-MYC, AXL and FOXP1." (PMID 31472685, 2019). "In line with our in vitro findings, CDKI‐73 also reduced the level of Mcl‐1 and Bcl‐2, which was accompanied by induction of apoptosis indicated by cleavage of PARP when compared with the vehicle‐treated tumours." (PMID 31398271, 2019). "In this study, Cx43 and Bcl-2 expression as a potential predictive molecular marker of taxane drug sensitivity was investigated in HNSCC cell lines and tumor cells." (PMID 31766723, 2019). "In patients with DHL/THL, the cooperation between BCL2-induced inhibition of apoptosis and MYC-induced genomic instability promotes oncogenesis and tumour progression." (PMID 31315646, 2019).
tumor (continued). "The anti-tumor mechanism analyzed from the western blotting result showed that GA-Se@DOX induced the apoptosis of HepG2 cells via activating caspase and Bcl-2 signaling pathways." (PMID 31928356, 2019). "We split patients in the training cohort in five groups, according to the tumor BCL6, CD11c, BCL2, and LAIR1 expression (high/low), and then performed Kaplan Meier analyses to determine the overall survival (OS) in the function of the expression level." (PMID 31336593, 2019). "Most of them promote tumour development, e.g., cell cycle activators (c-Myc and CDK4/6), anti-apoptotic factor (Bcl2), activators of invasion (c-Met, Notch1 and Fra-1) and epithelial-mesenchymal transition inducing factor (SNAIL)." (PMID 31658284, 2019). "In these cases, significant inhibition of tumor growth was observed, which correlated with reduced expression of target proteins, such as c-MYC and BCL-2, in tumors." (PMID 31472685, 2019). "Previous studies of MM have well-characterized miR-16-5p as both a tumor suppressor by targeting oncogenes BCL2 and CCND123–25, and as a remarkably under-expressed miRNA in MM tumor cells and tissues." (PMID 31406207, 2019). "This phenotype can be blocked by forced expression of Bcl-2 and Bcl-xL, suggesting the functional interaction of Bcl-2/Bcl-xL and HRK in tumor cells." (PMID 30774992, 2019). "According to this observation, in most DLBCL cell lines, effective tumor cell killing requires the concomitant inhibition of BCL6 and BCL2." (PMID 31336593, 2019). "In summary, we identified, for the first time, that the tumor suppressor miRNA miR-100-3p directly targeted to BMPR2 and consequently regulated the ERK/AKT and Bax/Bcl2-Caspase3 signaling pathways in GC." (PMID 31889906, 2019). "Inhibition of tumor growth was accompanied by a reduction in anti-apoptotic Bcl-2, Bcl-XL, Mcl-1, survivin, and VEGF in tumor tissue, and decreased expression of proliferation mediators cyclin D and c-Myc." (PMID 31671769, 2019). "In this study, based on our in vitro and in vivo results and literature data, we introduce a novel, comprehensive network of common tumor-related proteins, such as PD-1, MET, RAF1, STAT3, BCL2, or mTOR." (PMID 31681332, 2019). "In vivo studies showed that knockdown of hsa_circ_006100 delayed tumour growth, reduced PCNA expression and upregulated miR‐195 and BCL‐2 expression which was restored by miR‐195 inhibition due to GPRC5A/EGFR signalling, and changed the EMT phenotype in vivo." (PMID 31318114, 2019). "miR-100-3p acted as a tumor-suppressor miRNA that down-regulated BMPR2, which consequently inhibited the ERK/AKT signaling and activated Bax/Bcl2/Caspase3 signaling." (PMID 31889906, 2019). "Treatment with R-PHQ and S-PHQ clearly induced the apoptosis of tumor cells, significantly increased the expression of Bax, and remarkably inhibited the expression of Bcl-2 and vascular endothelial growth factor (VEGF) in H22 tumor tissues." (PMID 30769948, 2019). "The destruction of the balance between Bcl-2 and BAX can result in tumor cells that are resistant to chemotherapy drugs." (PMID 30842340, 2019). "In the case, PLK1, BCL2, and STAT3, three important proteins with high relevance in tumor growth, were selected." (PMID 31888119, 2019). "A major trigger for mitochondrial clearance in tumor cells is mitochondrial membrane depolarization and hypoxia, activating PTEN-induced putative kinase 1 (PINK1)/Parkin pathway or through Bcl-2." (PMID 31889941, 2019).
tumor (continued). "BCL2 expression was found positively correlated with HOX family gene, and negatively correlated with tumor suppressor microRNA such as miR-195, miR-497, and miR-193b." (PMID 31253168, 2019). "It has many effects on tumor cells, which include cyclin-dependent kinase (CDK) regulation and expression regulation of B-cell lymphoma 2 (Bcl2) proteins (Bax, Bcl-2, Bcl-xL) and caspases." (PMID 31717922, 2019). "The PI3K/AKT pathway is closely related to the proliferation, differentiation, apoptosis, migration, and adhesion of tumor cells involving multiple targets, including EGFR, BCL2, GSK3B, CDK2, and CDK4." (PMID 31406500, 2019). "Once cells aberrantly proliferate, apoptosis suppressors Bcl-xL and Bcl-2 are activated via persistent STAT5 signaling, driving tumor cell survival." (PMID 31684144, 2019). "Nevertheless, the combination of Bcl‐2 inhibition by ABT263 and Bim upregulation by BGJ398 triggers substantial caspase activation in the tumour, which likely contributes to the enhanced cell death following treatment with BGJ398 + ABT263." (PMID 30537101, 2019). "The expression of BCL2 in the primordial reserve both in patients that had or had not received chemotherapy rules out the possibility that BCL2 expression may be linked to a chemo-treatment response, supporting the idea that it is related to the presence of an extragonadal tumor." (PMID 30857552, 2019). "Mir-195 has been shown to target Bcl-2, inducing apoptosis, and target FASN, HMGCR, ACACA and CYP27B1 in hormone-receptor positive breast cancer cell lines, suppressing tumour growth, EMT, invasion and metastasis." (PMID 31077182, 2019). "We used western blot and fluorescent microscopy to investigate protein level and localization of Cx43 and Bcl-2 in each cell line and immunohistochemistry for the same reason in formalin-fixed, paraffin-embedded (FFPE) tumor samples." (PMID 31766723, 2019). "The most potent combination tested: MYC, BCL2, P53dd, and CCND3 resulted in tumor formation in all mice within 38 days." (PMID 31586074, 2019). "IHC on xenograft tumors with antibodies to apoptosis related genes including BCL-2 and BAX also confirmed Cisplatin with ASC-J9® treatment had the best suppressive effects on xenografted miBCa tumor growth via increased miBCa cell apoptosis." (PMID 31234917, 2019). "In vivo, the downregulation of MARCH1 by treatment with SAF markedly inhibited tumor growth, suggesting that SAF partly blocks MARCH1 and further regulates the PI3K/AKT/β-catenin and antiapoptosis Mcl-1/Bcl-2 signaling cascade in the HCC nude mouse model." (PMID 30678274, 2019). "Analogous alterations in the BCL-2 network, recently observed in other cellular settings, have been postulated to create a BCL-2 addiction used by BH3-mimetics to eliminate tumor cells." (PMID 29682179, 2018). "Beyond targeting anti-apoptotic BCL-2 proteins, increasing interest has centred on developing drugs that directly activate BAX and BAK in order to kill tumour cells." (PMID 29769323, 2018). "Western blot analysis by using tumor lysates showed that silenced PPARα reduced LC3-II levels and increased Bcl2 protein levels." (PMID 30519260, 2018). "Bcl-2 overall mean expression was 63% (SD: 38.6%), 74%, 76% and 38% in grade I, II and III tumours, respectively (p = 0.2262)." (PMID 30183767, 2018). "miR-34a is a proapoptotic tumor-suppressive miRNA that targets multiple genes including MYCN and BCL2 that was encapsulated in a nanoparticle coated with antibodies to disialoganglioside GD2." (PMID 29854719, 2018). "In this article, we identified that anti-apoptosis related gene Bcl-2, and tumor suppressor protein PTEN participated in this IL-23 and HNF4α mediated tumor progression." (PMID 29983862, 2018).
tumor (continued). "This profile accounted for both the early anti-tumor activity that was observed in CLL and the dose-limiting toxicity of thrombocytopenia, with BCL-2 inhibition driving the former and BCL-XL inhibition the latter." (PMID 30406027, 2018). "LOH of DCC, BCL2, and SMAD4 were validated using microsatellite marker quantification between tumor and matched normal samples for each specific locus." (PMID 30219970, 2018). "NF-κB plays a pivotal role in linking chronic inflammation to cancer development through its ability to upregulate several inflammatory and tumor promoting cytokines such as IL-6, IL-1α, and TNF-α, as well as survival genes such as BCL2 and BCLXL." (PMID 29772687, 2018). "We recently demonstrated that tumor suppressive miRNA target BCL-W, BCL-2, and BCL-X as a novel, miRNA-mediated mechanism of apoptosis induced by the oncogenic transcription factor Myc." (PMID 30671383, 2018). "Molecular analysis of the tumor tissues showed that melatonin decreased the levels of p-Akt, p-ERK, cyclin D1, PCNA, Bcl-2, Vimentin, Snail, HIF-1α, and VEGF, but upregulated the expressions of Bax and E-cadherin." (PMID 29725496, 2018). "One of these genes was associated with mitochondrial fission (fission 1, or FIS1), one with apoptosis (bcl-2 homologous antagonist killer, or BAK1) and one with tumor suppression (stratifin, or SFN)." (PMID 30404157, 2018). "At this point, it would be interesting to analyze in human biopsies BCL-2, MCL-1 or BCL-xL levels during follow-up to test their correlation with the tumor response under sorafenib." (PMID 29682179, 2018). "The Δ% of K was positively correlated with the Δ% values of tumor size, Ki-67, CA125 and Bcl-2 and was negatively correlated with the Δ% values of apoptosis and tumor necrosis." (PMID 30518386, 2018). "Anti-apoptotic proteins like BCL-2, BCL-XL, and MCL-1 are well-known for maintaining tumor cell survival and are therefore attractive drug targets." (PMID 30406027, 2018). "It was reported that tumor cells acquire TRAIL resistance by the upregulation of XIAP, c-FLIP, Bcl2, and Bcl-xL as antiapoptotic proteins, and activation of phosphoinositide 3-kinase (PI3K), protein kinase B (AKT), and NF-κB as proliferation activators." (PMID 29772677, 2018). "We found that treatment with MET NVB + Endo was most effective in inhibiting tumor growth, decreasing expression of CD31, VEGF, HIF-1α, and CEPs, and reducing side effects, inducing apoptosis, such as expression of Bcl-2, Bax and caspase-3." (PMID 30305062, 2018). "As for MAT2B, it has been demonstrated to inhibit cell growth, colony formation and induction of apoptosis of A375 and mel-rm cell lines in vitro, affect the expression of BCL2 and XAF1 proteins, and prolong the growth of transplanted tumor in vivo." (PMID 30379973, 2018). "The balance of BCL-2 family proteins (such as proapoptotic proteins BAK and BAD), as well as anti-apoptotic proteins BCL-2 and MCL-17, regulates tumor cell apoptosis." (PMID 29416644, 2018). "As a consequence of BCL2 down-regulation and a rise in BAX level, we detected a remarkable increase in apoptosis levels in tumor cells, whereas PBMCs proved to be unaffected." (PMID 30120339, 2018).
tumor (continued). "First, Bcl-2 overexpression would only transiently occur during the short (<1 week) window in which NSC survival is critical for maximum prodrug conversion and tumor tropism." (PMID 30026762, 2018). "So far, the tumor suppressor function of miR‐15/16, which targets important drivers of malignant growth such as FGF2 and the anti‐apoptotic protein Bcl‐2, has been well established in various tumor types including prostate, lung, ovarian, and MPM." (PMID 29094504, 2018). "ABT-737 mimics the BH3-domain of pro-apoptotic BAD and interacts with BCL-2, BCL-XL and BCL-W, displacing BH3-only proteins to trigger apoptosis in cell lines and restrict tumour growth in xenograft models." (PMID 29769323, 2018). "Therefore, the objective of our study was to investigate whether the ADC value of DWI, and K and D values of DKI can be used to assess the early response to DTX chemotherapy in induced rat EOC by correlating with the tumor size, Ki-67, Bcl-2, apoptosis and tumor necrosis." (PMID 30518386, 2018). "Combining it with the Bcl-2 inhibitor ABT-737 or vinblastine, however, markedly decreased tumor burden and prolonged survival relative to control." (PMID 30279971, 2018). "We found that NEAT1 inhibition plus DDP in vivo inhibited the BCL-2/caspase-3 levels and increased the BAX expression for tumor apoptosis, and also repressed the cyclin D1/CDK4 expression for cell cycle arrest." (PMID 29654165, 2018). "Knockdown of NEAT1 up-regulated the tumor suppressor miR-34c to inhibit cell proliferation, induce apoptosis, and cell cycle arrest via BCL-2 and cyclin D1 pathway, which elevated the sensitivity to DDP-induced chemotherapy for tumor regression." (PMID 29654165, 2018). "On the other hand, when we took into account the tumor expression profile, DNMT3A overexpression was significantly correlated with BCL2 protein expression (P = 0.0261)." (PMID 29721185, 2018). "In pathway in cancer and cell cycle, Bcl2, VEGFA, PTEN, Jun, Fos, APC2 were up-regulated and Ccna2, Cdc25a, Mcm3, Mcm6, Ccnb2, Mcm5, Cdk1, Gadd45a, Myc were down-regulated in the MMQ tumor stem-like cells." (PMID 28163656, 2017). "The tumor cells were diffusely positive for CD20, PAX-5, Bcl-2 and follicular dendritic cells were positive for CD21, CD23." (PMID 28353588, 2017). "Bcl2, VEGFA, PTEN, Jun, Fos, APC2 were up-regulated and Ccna2, Cdc25a, Mcm3, Mcm6, Ccnb2, Mcm5, Cdk1, Gadd45a, Myc were down-regulated in MMQ tumor stem-like cells group." (PMID 28163656, 2017). "Prediction of potential targets for the identified miRNAs indicates the overexpression of KRAS, BCL2 and down-regulation of PTEN in PCa tumor tissues." (PMID 29268752, 2017). "In general, epithelial cell lines and tumors were associated with cancer stem cell markers (CD24, ALDH1A1, and PROM1), markers of tumor aggressiveness (MYCL1 and ASCL1), and markers of apoptosis (BCL2 and BCL2L11)." (PMID 28212573, 2017). "Consistent with the results in vitro, we found that lncRNA CTA overexpression decreased the accumulation of LC3-II isoforms in tumor tissues, and exerted a synergic effect with DOX in increasing the levels of caspase 3 and in decreasing the levels of Bcl-2." (PMID 28415557, 2017). "First, an IHC assay was performed to assess the expression of Bcl-2, Twist1 and EMT-related proteins in 82 OSCC tumor tissues and 24 para-neoplastic tissues." (PMID 28032603, 2017). "There is clearly a role for BIM in tumour cell death arising from combined ERK1/2 pathway and BCL2/BCL‐XL inhibition, but this varies across tumour type and with oncogenic driver mutation." (PMID 28548464, 2017). "The synergistic anti-tumor activity of JQ1 and ABT-263 is through up-regulation of Bim, and disturbing the interaction of Bim with Bcl-2 and Mcl-1." (PMID 29156797, 2017).